PTN (pleiotrophin)
Diseases named in the same sentence as PTN in open-access papers (continued):
Sharing a sentence is not in itself a finding about the gene and the disease.
osteoporosis (7 papers, 2012 to 2025). A condition of reduced bone mass, with decreased cortical thickness and a decrease in the number and size of the trabeculae of cancellous bone (but normal chemical composition), resulting in increased fracture incidence. "Another study investigating the relationships between osteoporosis and PTN genomic polymorphisms demonstrated that the promoter region polymorphisms of PTN were significantly associated with osteoporosis phenotypes in postmenopausal women." (PMID 40149671, 2025). "In postmenopausal women, PTN gene promoter −1227C>T (rs321198) polymorphism contributed to the genetic background of osteoporosis." (PMID 32153561, 2020). "The studies found that polymorphisms in the PTN gene promoter were significantly associated with bone mineral density in patients, indicating that PTN might be a potential pathogenic gene for osteoporosis." (PMID 40149671, 2025). "Previous studies have indicated that pleiotrophin (PTN) was a secretory factor involved in several biological processes, such as angiogenesis, neural development, and abnormal osteogenic functions in osteoporosis." (PMID 40149671, 2025). "A study employing microarray analysis revealed that PTN expression is significantly decreased in osteoblasts derived from patients with osteoporosis." (PMID 40149671, 2025). "One study investigated the relationships between genotypes of PTN and phenotypes of osteoporosis in postmenopausal women." (PMID 40149671, 2025). "Fracture-healing experiments in osteoporosis rats were also conducted to evaluate the osteogenic functions of PTN in vivo." (PMID 40149671, 2025). "PTN is a diffusible factor usually liberated from osteoblasts and its over-expression is expected to stimulate the osteoblasts and attenuate osteoporosis development." (PMID 22470446, 2012). "Moreover, the possible protective action of pleiotrophin (PTN) over-expression in microgravity-induced osteoporosis was investigated by utilizing PTN-over-expressing mice." (PMID 22470446, 2012). "We selected PTN-Tg mice to investigate whether these mice were protected from space related osteoporosis and whether the PTN over-expression could be considered a countermeasure for the bone loss observed in microgravity." (PMID 22438896, 2012). "Our study revealed that PTN may be a potential therapeutic target in osteoporosis." (PMID 40149671, 2025). "Therefore, it can be speculated that PTN participates in the pathogenesis of osteoporosis; however, the biological mechanisms remain unclear." (PMID 40149671, 2025). "Therefore, the authors speculated that PTN may be involved in the pathogenesis of osteoporosis." (PMID 40149671, 2025). "The study revealed that PTN expression was significantly lower (by 6.2-fold) in patients with osteoporosis than in those without osteoporosis." (PMID 40149671, 2025).
Insulin resistance (6 papers, 2019 to 2024). Increased resistance towards insulin, that is, diminished effectiveness of insulin in reducing blood glucose levels. "Pleiotrophin deletion is associated with a lipodystrophic phenotype, altered energy metabolism and insulin resistance." (PMID 31031625, 2019). "PTN is a cytokine which when knocked out in high-fat diet fed mice, protects against insulin resistance, obesity and neuroinflammation." (PMID 38918843, 2024). "All in all, this review proposes pleiotrophin as a druggable target to prevent from the development of insulin-resistance-related pathologies." (PMID 37484951, 2023). "Pleiotrophin (PTN) is a heparin-binding cytokine that is widely expressed during early development and increases in maternal circulation during pregnancy.Aged PTN-deficient mice exhibit insulin resistance, suggesting a role in metabolic control." (PMID 35250852, 2022). "Therefore, it has been proposed that absence of pleiotrophin has a protective role against high fat diet-induced insulin resistance and obesity in rodents." (PMID 37484951, 2023). "Moreover, although the administration of a HFD induced hyperinsulinemia and insulin resistance in the HFD-Ptn+/+ mice, neither insulinemia nor the insulin resistance index increased in HFD-Ptn−/− mice, suggesting a protective role of pleiotrophin deletion in the HFD-induced insulin resistance." (PMID 34502170, 2021).
autoimmune disease (5 papers, 2016 to 2023). A disorder resulting from loss of function or tissue destruction of an organ or multiple organs, arising from humoral or cellular immune responses of the individual to their own tissue constituents. "MK and PTN were also shown to be associated with different diseases, including cancers and autoimmune diseases such as rheumatoid arthritis (RA), systemic lupus erythematosus (SLE), and multiple sclerosis (MS)." (PMID 37850119, 2023). "MK and PTN were also shown to be associated with autoimmune diseases such as RA, MS, cancers, and the inhibition of HIV infection." (PMID 37850119, 2023). "Emerging evidence suggests that two heparin-binding growth factor, midkine and pleiotrophin are implicated in the pathogenesis of autoimmune diseases including SLE." (PMID 27903979, 2017). "Though expressed during injury and in several autoimmune diseases, PTN function in immune regulation remains unexplored." (PMID 36828390, 2023). "Despite increasing evidence of the involvement of midkine in the pathogenesis of autoimmune diseases, the data on pleiotrophin in these diseases are very limited." (PMID 27903979, 2017). "Besides, hyaluronan (HA) has been shown to inhibit the toll-like receptor (TLR) 4 activity to downregulate PTN level in a Th1-type autoimmune disease model, implicating PTN as a TLR4-responsive gene." (PMID 32153561, 2020). "Up to date, the evidence of pleiotrophin in autoimmune diseases is also very limited." (PMID 27903979, 2017). "Third, our approach may not be useful in patients with Graves’ disease or chronic lymphocytic thyroiditis; we observed elevated PTN/Tg ratios in benign nodules within thyroid glands affected by these autoimmune disease." (PMID 26914549, 2016).
ischemia (5 papers, 2013 to 2023). A hypoperfusion of the BLOOD through an organ or tissue caused by a PATHOLOGIC CONSTRICTION or obstruction of its BLOOD VESSELS, or an absence of BLOOD CIRCULATION. "Likewise, pleiotrophin has displayed angiogenic properties and the stimulated formation of new blood vessels in a cardiac model of ischemia." (PMID 34439416, 2021). "Pleiotrophin (PTN) is a cytokine found highly upregulated in the brain in different disorders characterized by overt neuroinflammation such as neurodegenerative diseases, drug addiction, traumatic injury, and ischemia." (PMID 28259175, 2017). "Pleiotrophin is a cytokine that is found highly upregulated in diverse pathologies of the CNS characterized by overt neuroinflammation including neurodegenerative diseases, addictive disorders, ischemia, and neuropathic pain." (PMID 28259175, 2017).
papillary thyroid cancer (5 papers, 2016 to 2020). "Interestingly, another study also concluded that CRNDE up-regulated pleiotrophin (PTN) by competitively binding to miR-384, while suggesting that the CRNDE/miR-384/PTN axis promoted papillary thyroid cancer cell proliferation, invasion and migration." (PMID 30819221, 2019). "The expression of PTN in papillary thyroid cancer (PTC) is unknown." (PMID 26914549, 2016). "Further mechanistic studies highlighted the important roles of CRNDE/miR-384/PTN axis in the progression of PTC, in which CRNDE promotes cell proliferation, invasion and migration at least partly via competitively binding miR-384 in papillary thyroid cancer." (PMID 29299168, 2017).
triple-negative breast carcinoma (5 papers, 2023 to 2026). An invasive breast carcinoma which is negative for expression of estrogen receptor (ER), progesterone receptor (PR), and human epidermal growth factor receptor 2 (HER2). "This review integrates current evidence on PTN's roles from normal mammary development, where it can delay ductal outgrowth, to triple negative breast cancer, where it promotes lung metastasis and correlates with poor survival." (PMID 42193935, 2026). "Doxorubicin enhanced both PTPRZ1 and PTN expression in the triple-negative breast cancer MDA-MB-231 and MDA-MB-453 cells, promoting cell proliferation and inhibiting apoptosis through PTPRZ1-dependent activation of NFκΒ." (PMID 37175798, 2023). "We used 3B10 to determine whether PTN is important for the progression of established breast tumors by exploiting an orthotopic triple-negative breast cancer (TNBC) model, 4T1." (PMID 36828390, 2023). "In triple-negative breast cancer (TNBC) tissues that had relapsed after chemotherapy, the expression of PTN and its receptor PTPRZ1 was found to be elevated, which was closely linked to a poor prognosis." (PMID 39759507, 2024).
astrocytoma (4 papers, 2018 to 2025). "Because the seven subpopulations of astrocytoma involved the PTN signaling network pathway in both Incoming communication and Outgoing communication, we initiated further studies on the PTN pathway." (PMID 39403379, 2024). "Overall, the seven TAM populations were observed to be contributing in an increased capacity to pathways such as SPP1, COMPLEMENT, GALECTIN and PTN compared to their counterparts in IDH-mutant astrocytoma." (PMID 38012322, 2023). "Compared to the IDH-mutant astrocytoma, GBM exhibited increased information flow in multiple pathways including GALECTIN, COMPLEMENT, MIF, SPP, and PTN." (PMID 38012322, 2023). "Therefore, we conducted further analysis of the PTN pathway and discovered that PTPRZ1 exhibits high expression in various subclusters of astrocytoma." (PMID 39403379, 2024). "Compared to normal brain tissues, the PTN expression increases in low-grade astrocytomas, but the high PTN expression is not related to increasing malignancy grade, proliferation rate, microvascular density and poor overall survival." (PMID 30427932, 2018).
hepatocellular carcinoma (4 papers, 2017 to 2025). A malignant tumor that arises from hepatocytes. "We focused our study on the effect of miR‐384 and PTN for the modulation of hepatoma cell proliferation and metastasis." (PMID 28557334, 2017). "Our findings demonstrate that PTN promotes de novo lipogenesis of hepatoma cells by up‐regulating the lipogenic enzymes FAS via the N‐syndecan/PI3K/Akt/mTORC1/SREBP‐1c signalling pathway." (PMID 28557334, 2017). "HBx inhibits miR‐384, which results in PTN overexpression to promote proliferation, metastasis and lipogenesis in hepatoma cells." (PMID 28557334, 2017). "The IHC results showed that PTN was expressed in HSCs, hepatocytes and hepatoma cells, PTN protein in HCC was localized in the cytoplasm, and the expression of PTN was elevated in some patients with steatosis." (PMID 28557334, 2017). "The expression level of FAS, which was identified as the target gene of SREBP‐1c, was also significantly increased in PTN‐transfected hepatoma cells compared with control cells." (PMID 28557334, 2017). "The immunohistochemical results showed that the expression of PTN was increased in some patients with steatosis, suggesting that PTN was related to abnormal lipid metabolism in hepatoma cells." (PMID 28557334, 2017). "Proliferation, angiogenesis and de novo lipogenesis in hepatoma cells regulated by PTN are important for the progression of HCC." (PMID 28557334, 2017). "We found that miR‐384 was capable of down‐regulating PTN in hepatoma cells by directly binding to its 3′UTR." (PMID 28557334, 2017). "The activation of N‐syndecan/PI3K/AKT/mTORC1 pathways was regulated by PTN in HCC, which was considered the key mechanism underlying the hepatoma cell proliferative and migratory capacity induced by HBx." (PMID 28557334, 2017). "PTN acts as a growth factor via N‐syndecan on hepatoma cells to promote cell proliferation, metastasis and lipogenesis." (PMID 28557334, 2017). "We aimed to determine the role of PTN in hepatoma cell lipogenesis." (PMID 28557334, 2017). "The reason for the opposite results for hepatoma cells compared with pre‐adipocytes regulated by PTN in lipid metabolism remains unknown, but many studies have detected differences in energy metabolism between tumour cells and normal cells." (PMID 28557334, 2017). "The IHC results showed that PTN was expressed in HSCs, hepatocytes and hepatoma cells." (PMID 28557334, 2017). "The up‐regulation of PTN expression could promote hepatoma cell proliferation and metastasis." (PMID 28557334, 2017). "However, little is known regarding whether PTN is involved in the lipogenesis of hepatoma cells induced by HBV." (PMID 28557334, 2017). "Through the N-syndecan/PI3K/Akt/mTORC1 pathway, PTN could promote the expression of the SREBP-1c gene, further facilitating denovo lipogenesis by up-regulating the lipogenic enzyme FAS in hepatocellular carcinoma." (PMID 30427932, 2018).
keloid (4 papers, 2010 to 2022). An irregularly shaped, elevated mark on the skin caused by deposits of excessive amounts of collagen during wound healing. "In conclusion, we identified four immune signaling molecules associated with keloid (LGR5, PTN, JAG1, and DKK1)." (PMID 35967426, 2022). "We observed that the specific and significant outgoing signal patterns of SC in the earlobe keloid were PTN, SEMA3, PDGF, and EGF." (PMID 36388926, 2022). "In the GSE7890 dataset, DKK1 and PTN were downregulated in keloid, whereas JAG1 and LGR5 were upregulated in keloid." (PMID 35967426, 2022). "The higher-level expression of PTN in hypertrophic scars and the low-level expression in keloids suggest different pathomechanisms between keloids hypertrophic scars." (PMID 32085797, 2020). "However, the results of the present study revealed for the first time the downregulation of five genes (ANXA1, ASPN, IGFBP7, LGALS1, and PTN) which is in contrast to the upregulation of the same genes in African and Caucasian keloid samples." (PMID 32085797, 2020). "However, in our study, an approximate 8-fold significant upregulation (P = .041) was observed in keloid biopsies for PTN, which correlates to PTN upregulation reported in keloid biopsies by Chen et al17 and Hu et al13 by microarray analysis." (PMID 20418938, 2010). "Through immunohistochemistry staining, we found that the expression of DKK1 and PTN was lower in the keloid, while JAG1 and LGR5 showed a higher expression in the keloid." (PMID 35967426, 2022). "We found that the expression of DKK1 and PTN was downregulated, while the expression of JAG1 and LGR5 was upregulated in keloid." (PMID 35967426, 2022). "A statistically significant (P < .05) differential expression and a fold change of more than 2 were determined between keloid margin and internal control biopsy samples for 10 genes, including ACAN, ASPN, C5orf13, HIF1A, IGFBP7, INHBA, LGALS1, PTN, SERPINH1, and TNFAIP6." (PMID 20418938, 2010). "Finally, four genes related to keloid (LGR5, PTN, JAG1, and DKK1) were identified, and we further studied keloid pathogenesis, which may provide new ideas and insights for keloid treatment." (PMID 35967426, 2022).
metastatic disease (4 papers, 2021 to 2024). "PTN, MK, PVRL4, EPHA2, TFPI-2, hK11, SYND1, ANGPT2 and hK14 were found elevated in the metastatic disease when compared to cancer-free, CPG1 and/or CPG5 groups." (PMID 33288843, 2021). "eNOS may in turn upregulate pleiotrophin (PTN), expression through ERK activity, increasing tumor and endothelial migration, laying the groundwork for metastatic disease." (PMID 33513777, 2021). "PTN was selected for further investigations as it was elevated in both aggressive non-metastatic as well as metastatic disease." (PMID 33288843, 2021). "In addition, individuals with menin-low tumors that expressed PTN were more likely to exhibit metastatic disease and have shorter disease-free survival compared to their menin-low counterparts that did not express PTN." (PMID 39336822, 2024). "Consequently, blocking PTN in combination with anti–PD-1 therapy and Abraxane in mice with established TNBC metastatic disease had a significant therapeutic benefit, especially compared with anti–PD-1 plus Abraxane alone, which is currently being used to treat metastatic TNBC patients." (PMID 36828390, 2023).
multiple sclerosis (4 papers, 2021 to 2025). A progressive autoimmune disorder affecting the central nervous system resulting in demyelination. "PTN upregulation in multiple sclerosis astrocytes was shown to be neuroprotective as PTN was shown to reduce proinflammatory signalling in astrocytes and promote neuronal survival." (PMID 40301248, 2025). "Two other proteins, ADGRG1 and PTN, were significant across the groups (controls and multiple sclerosis subtypes) according to Kruskal–Wallis/ANOVA test (FDR = 0.008 and FDR = 0.046, respectively)." (PMID 38978729, 2024). "Here, we report the upregulation of pleiotrophin (PTN) by mouse and human astrocytes in multiple sclerosis (MS) and its preclinical model experimental autoimmune encephalomyelitis (EAE)." (PMID 35046956, 2021).
Obesity (4 papers, 2017 to 2024). Accumulation of substantial excess body fat. "As increased omental adipose tissue mass has a higher risk of obesity-associated metabolic diseases, PTN expression has therefore been proposed as a possible link between obesity, diabetes, and cardiovascular diseases." (PMID 37484951, 2023). "Additionally, β-carotene is also positively associated with enhanced reduced response of metabolite 1,5-anhydroglucitol and of proteins SERPINE1 (PAI-1) and pleiotrophin (PTN) which are all linked to obesity and T2DM." (PMID 28194237, 2017). "The aim of this study was to determine the role of pleiotrophin in hepatic lipid metabolism and in the metabolic crosstalk between the liver and brown and white adipose tissue (AT) in a high-fat diet-induced (HFD) obesity mice model." (PMID 34502170, 2021).
ovarian carcinoma (4 papers, 2012 to 2025). A malignant neoplasm originating from the surface ovarian epithelium. "Notably, we observed that high expression of SDC4, a critical component of PTN signaling, is significantly associated with poor prognosis in ovarian cancer patients, highlighting its potential as a prognostic biomarker." (PMID 40416874, 2025). "In our analysis, we revealed that PTN is one of major driven signaling pathway in ovarian cancer cells that affect the other cell types in the TME, suggesting the importance of PTN signaling in the TME of HGSOC." (PMID 40416874, 2025). "Further analysis demonstrated that PTN signaling was particularly strong in “B cells,” “ovarian cancer,” “erythrocytes,” and “fibroblasts,” suggesting their pivotal roles in the TME." (PMID 40416874, 2025). "Among these genes from PTN signaling, we further explored the relationship between the expression of these genes and the overall survival of patients with ovarian cancer." (PMID 40416874, 2025). "The genes in the PTN signaling were mainly expressed in the cell types including “fibroblast” and “ovarian cancer”." (PMID 40416874, 2025). "Results of the present study are the first to identify a high level of expression of the PTN gene in GE of ovarian carcinoma in laying hens." (PMID 22496782, 2012). "In ovarian cancer studies, PTN was expressed, produced, and secreted in a panel of EOC cell lines." (PMID 40416874, 2025). "Notably, PTN is the only signaling pathway originating from “ovarian cancer” and received by all other cell types." (PMID 40416874, 2025). "Indeed, CTSB, SERPINB11, A2M, and PTN are genes that we reported to be most abundant in the GE of ovarian cancers in laying hens." (PMID 23843947, 2013).